INS (insulin)
Diseases named in the same sentence as INS in open-access papers (continued):
Sharing a sentence is not in itself a finding about the gene and the disease.
cancer (continued). "For example, PREX2 is an oncogene that interacts with PTEN gene product to inhibit PTEN phosphatase activity, thus activating the PI3K signaling pathway, which plays a role in insulin signaling pathways, and its mutations or overexpression have been observed in some cancers." (PMID 35654793, 2022). "The well-known antihyperglycemic effects of metformin may lower cancer risk by decreasing circulating insulin at the organismal level." (PMID 34255745, 2021). "Interestingly, our recent preliminary studies have shown that exosomes derived from co-cultures of mouse PSCs and cancer cells cause mouse beta cell dysfunction as evidenced by significantly reduce insulin secretion." (PMID 34680372, 2021). "Some studies have indicated a clear association between cancer and the insulin/IGF-1 axis." (PMID 33479372, 2021). "The increased risk of cancers of the digestive system, uterus, kidney, and bladder may be mediated by alterations in insulin signaling, growth factors, adipose tissue-derived inflammation, and hormone levels." (PMID 34906131, 2021). "There have been concerns regarding whether exogenous insulin, especially insulin glargine, could increase the risk of cancer." (PMID 34830886, 2021). "In female patients diagnosed with various cancers, 10-weeks of combined aerobic and resistance ET led to increased expression of skeletal muscle GLUT4 protein, suggesting that ET causes insulin-sensitizing molecular adaptations in skeletal muscle of cancer patients." (PMID 33801684, 2021). "This leads to an increase in endogenous insulin levels and may theoretically be associated with an increased risk of cancer." (PMID 33562380, 2021). "In addition, sugary beverages can promote insulin-glucose dysregulation, oxidative stress, inflammation, and adiposity and finally cause steroid hormone imbalances, which collectively increase cancer risk 96-98." (PMID 33854607, 2021). "Also, monotherapy of SU or insulin showed elevated risk of malignancy development, however, combined therapy with metformin abolishes the adverse effect on cancer." (PMID 34535145, 2021). "High weight variability is associated with elevated insulin and shorter telomere length, which may lead to an increased cancer risk." (PMID 33924149, 2021). "Biological mechanisms underlying associations between PA and cancer survival are under active investigation and may include reduced chronic inflammation and improved insulin sensitivity, metabolic function, and immune surveillance." (PMID 34572881, 2021). "In addition, several cohort studies showed that subjects with high insulin levels have an increased risk for certain types of cancers, in addition to a poor prognosis." (PMID 34681797, 2021). "Role of insulin in carcinogenesis was primarily found in studies with experimental animals where hyperglycemic and insulin deficient models depicted less aggressive and lower number of tumors with slower cancer progression." (PMID 34535145, 2021). "In addition, exogenous insulin has been associated with various adverse outcomes, including overall cancer mortality." (PMID 34169227, 2021). "The down-regulation of the GH/IGF-1/insulin system decreases cancer risk and increases longevity in animal models; however, in humans the results are somewhat contradictory, although genetic studies of the GH/IGF-1/insulin system support their involvement in human longevity." (PMID 34695806, 2021). "Since humans spend over 2/3 of their time in a postprandial state, it is logical to move forward under the supposition that lowering insulin could serve as a strategy to reduce risk of and progression of cancer." (PMID 34684564, 2021). "In fact, in many types of cancers,insulin induces resistance to chemotherapy and may evenbe associated with late diagnosis, especially in patientswith obesity and type-2 diabetes." (PMID 34308576, 2021).
cancer (continued). "If the natural supply of the nurturing hormone insulin was to be exploited by the most malignant cancer entity in close proximity, substantial associations with clinicopathological parameters and survival could be expected." (PMID 34638472, 2021). "On the other hand, insulin as anabolic hormone and growth factor may possibly increase the cancer risk in A-T patients." (PMID 32733823, 2020). "Importantly, the risk of CRC in T2DM is significantly modulated by antidiabetic treatment; insulin increases, while metformin, the first-choice oral antidiabetic, reduces cancer risk by interfering with hyperactive Notch1 and mTOR signaling." (PMID 32971867, 2020). "In addition, studies have also shown that, compared with the use of insulin or insulin secretagogues, metformin use lowers the risk of cancer and cancer-related deaths in patients with DM." (PMID 32717852, 2020). "In vivo evidence for the role of lactic acid-producing bacteria in gastric carcinogenesis has been the colonization of an Insulin-Gastrin transgenic mouse model with lactic acid-producing microbiota, resulting in gastrointestinal intraepithelial neoplasia and upregulation of cancer-associated genes." (PMID 32650561, 2020). "A population-based cohort study demonstrated that patients treated with SU showed an increased rate of cancer-associated mortality, which was identical to that found in insulin-treated patients, as compared to the mortality rate in patients treated with metformin alone." (PMID 32498358, 2020). "Cancer cells are also associated with INS insensitivity (resistance), due to high oxidative stress, especially during malignant transformation, and this could be an earlier event of carcinogenesis." (PMID 32046158, 2020). "Importantly, high levels of fasting blood insulin have been associated with increased risk of cancer in general, and more precisely, of breast, pancreas, and prostate cancers." (PMID 31906264, 2020). "Moreover, microenvironmental acidification and even systemic metabolic acidosis in cancer are linked with INS resistance, both phenomena being a reflection of the metabolic complications of cancer, the latter in advanced and disseminated disease." (PMID 32046158, 2020). "Known mechanisms associated with body fatness, such as sex hormones, insulin, and inflammation, may explain part of the association between recreational screen time and cancer risk." (PMID 32746843, 2020). "The relevance of that study was not only to have disclosed a biological difference for the two IR isoform variants (which are equally activated by insulin) but to have provided a clear cancer-promoting role to the IR, previously thought to be linked to cancer only due to metabolic requirements." (PMID 33266015, 2020). "Alcohol consumption might also lower cancer risk by other mechanisms, such as increased insulin sensitivity through increased adiponectin levels." (PMID 32701947, 2020). "The influence of insulin treatment on cancer risk is controversial." (PMID 32570776, 2020). "Insulin and/or leptin resistance (e.g., in obesity) may neutralize this tumor-suppressive pathway, increasing the risk of developing cancer." (PMID 32069948, 2020). "In addition, the researchers found a link with serum insulin: women with pre-existing medium or high insulin levels had higher risk reduction of female-specific cancer due to bariatric surgery." (PMID 32326591, 2020). "However, clinical data have suggested an interesting association between insulin–glargine and risk of cancer progression." (PMID 32498358, 2020). "Regarding antidiabetic medications, epidemiological studies suggest that whereas metformin could act as antineoplastic agent, therapies increasing circulating levels of insulin (i.e., sulfonylureas and exogenous insulin) could be related to higher cancer risk." (PMID 33383630, 2020).
cancer (continued). "The same study also found a positive association between fasting insulin levels and lung cancer, which may mean we need to re-evaluate the cancers we think of as being associated with metabolic dysregulation." (PMID 32705315, 2020). "Moreover, epidemiological studies demonstrated that higher serum insulin levels are associated with an increased risk of colon, breast and other cancers." (PMID 29143934, 2019). "High levels of insulin, as a consequence of insulin resistance in obese women, are also associated with an increased risk of post-menopausal breast cancer as well as an increased risk of cancer recurrence and mortality." (PMID 31380268, 2019). "A possible explanation of an increased mortality rate is the potential that insulin may increase the risk of developing cancer and atherosclerotic vascular diseases due to its atherogenic and mitogenic effects." (PMID 31877127, 2019). "This is the most promising setting for examining insulin/IGFs; as their robust associations with cancer outcomes indicate that they may be useful intermediate biomarkers." (PMID 30809194, 2019). "Obesity is implicated in carcinogenesis, and may affect cancer development through alterations in metabolism of insulin, insulin-like growth factors, chronic inflammation, adipokines and steroid hormones." (PMID 31711465, 2019). "Furthermore, metformin has several advantages in treating T2DM and associated cancer risks as compared to exogenous insulin and insulin secretalogues such as sulfonylurea drugs, which are reported to increase cancer risk and recurrence." (PMID 31831021, 2019). "The reduction of these insulin levels by whole grains may be an indirect way through which risk cancer reduction occurs." (PMID 29143934, 2019). "Consistently with these results, target prediction analysis revealed that miR-101-3p is involved in insulin signaling, lipid metabolism, cell proliferation, fibrogenesis, and cancer susceptibility, possibly representing a molecular signature in NAFLD during IR." (PMID 31671785, 2019). "Also, loss of cell cycle controlling gene CDKN2A, another commonly deleted gene in cancer, can break glucose equilibrium and cause increased insulin secretion by pancreatic β cells." (PMID 31313989, 2019). "The links between dietary carbohydrates and cancer risk are hypothesized to involve mechanisms that directly implicate players in insulin-mediated pathways across various tissue types as well as through modulation of IGF-1 bioactivity." (PMID 30895469, 2019). "Shortened telomere length, along with elevated insulin levels, may lead to increased risk of incident cancer, consequently resulting in elevated risk of death from cancer among those with high weight fluctuation." (PMID 31266987, 2019). "Physical exercise is inversely related to certain types of cancers and may reduce the risk of cancer by changing insulin and IGF and/or sex hormone levels, decreasing body weight and positively modulating immune function." (PMID 29697773, 2018). "Therefore, rosiglitazone as an insulin sensitizer should be appropriately applied in combination with 5-FU when taking cancer risk factors into consideration." (PMID 29743857, 2018). "Thus, metabolic dysfunction appears to increase the risk of cancer directly (due to an increased blood glucose and insulin) and by increasing the inflammation." (PMID 32984773, 2018). "Thus, the accumulation of fatty acid via de novo synthesis is proposed to result in enhanced risk of insulin insensitivity and cancer development." (PMID 29546056, 2018). "In two large prospective US cohorts, we evaluated the association of dietary (EDIH) and lifestyle (ELIH) indices developed to assess the insulin secretion potential of dietary and lifestyle behaviors and risk of developing cancers of the digestive system and its accessory organs." (PMID 30740588, 2018).
cancer (continued). "Metformin-mediated anti-cancer activities have been associated with both systemic and cellular regulatory activities, including lowering insulin levels, increasing insulin sensitivity, and activation of AMP-activated protein kinase (AMPK)/inhibition of mammalian target of rapamycin (mTOR)." (PMID 28947975, 2017). "Further, when stratified by exogenous E use, carriers of the AKT1 rs2494738 T and rs2498789 C alleles had an increased risk of CRC among nonusers; however, in E+P users, carriers of the rs2494738 T allele had a reduced risk of CRC (with 30% of the SNP–cancer association explained by insulin level)." (PMID 29023587, 2017). "Since there can be an insulin-independent glucose uptake in cancer cells, this may have an impact on the association between glucose, insulin and risk of CRC." (PMID 29233100, 2017). "Importantly, fasting regimens, which are associated with decreased levels of glucose and insulin, delayed the progression of cancer, have cancer preventive effects and increase the efficacy of chemotherapy agents." (PMID 28874144, 2017). "Being potent stimulators of insulin secretion, in principle, sulfonylureas might increase cancer risk." (PMID 29184536, 2017). "Chronic elevation of insulin concentrations may be one of the mechanisms explaining the positive association between dietary GI and cancer risk." (PMID 28114909, 2017). "However, insulin and insulin secretagogues are associated with higher cancer incidence and cancer-related mortality." (PMID 29379799, 2017). "Potential mechanisms may be TFAs could promote colonic mucosa irritation, insulin sensitivity and cell proliferation, which are positively associated with the incidence of cancers." (PMID 28915883, 2017). "To summarise, the present multi-country study addressed the clinically important question of whether some of the commonly used insulin treatments should be preferred over others as being safer with respect to cancer risk." (PMID 28573394, 2017). "However, epidemiological analyses have shown that T2DM patients under glycemic control, in particular, those who use insulin analogs, have at least a 30% higher risk for developing cancer in breast, colon, prostate, kidney and pancreas tissues." (PMID 28424632, 2017). "T2D and cancer share a number of metabolic risk factors, including high insulin/IGF, hyperglycemia, glucose deprivation, hypoxia and inflammation, but the underlined mechanism remains unclear." (PMID 27038142, 2016). "In addition, obese patients commonly present deregulation of insulin and/or insulin growth factor 1 (IGF1) that has also been linked to cancer because insulin is considered a strong mitogen factor and stimulates DNA synthesis." (PMID 26801617, 2016). "Obesity and diabetes are accompanied by increased cancer risk, which may be due to high circulating levels of the growth factors insulin and IGF." (PMID 28018856, 2016). "However, insulin use is associated with a significantly higher risk of either cancer or non-cancer death." (PMID 27906989, 2016). "Elevated levels of insulin have been shown to be a risk factor for a number of cancers." (PMID 26983499, 2016). "However, the associations between cancer, mortality risks and other antidiabetic drugs, such as insulin, sulfonylureas and thiazolidinedione, were controversial." (PMID 27271648, 2016). "However, we have not found a statistically significant difference in the risk of incident cancer between patients treated with insulin monotherapy or insulin in combination with metformin." (PMID 27152598, 2016). "Rather, sulfonylureas and insulin have been associated with increased risk for cancer." (PMID 27164115, 2016). "Elevated levels of insulin have been directly related to cancer risk and cancer recurrence." (PMID 27781180, 2016). "Commencing insulin therapy often leads to an increase in body weight, which may be associated with cardiovascular disease, cancer and increased mortality." (PMID 27031113, 2016).
cancer (continued). "Insulin has been shown to increase the risk of colorectal and other cancers by influencing the insulin-like growth factor system, which, in turn, may stimulate cellular proliferation and inhibit apoptosis." (PMID 27766252, 2016). "Current evidence from observational studies indicate harmful effect of insulin on the cancer risk." (PMID 27724912, 2016). "While improving metabolic control, elevated insulin level may increase cancer risk by dose-dependent effects on cellular differentiation, growth, proliferation, migration and invasion." (PMID 26939025, 2016). "Two of these studies suggested that insulin glargine may be associated with a higher risk of cancer than treatment with human insulin." (PMID 26242987, 2015). "It seems that long-term exposure to insulin has direct relevance to the cancer risk." (PMID 26541196, 2015). "Numerous studies have linked the insulin/IGF system with an increased risk of several cancers as well as a worse cancer prognosis, driving researchers’ interest in the enhancement of our understanding of these signaling pathways and the development of agents targeting them." (PMID 26029167, 2015). "Whether the risk of cancer is reduced with the presence of DM therapies, including oral hypoglycemia agents and insulin injection, was also investigated." (PMID 25978841, 2015). "Several studies have suggested that anti-diabetic insulin analogue treatment might increase cancer risk." (PMID 26242987, 2015). "Some studies have shown evidence that the rates of insulin secretion among individuals may influence the risk and progression of cancer." (PMID 25866823, 2015). "With regard to insulin injection therapy among all DM patients, rapid-acting (AHR = 0.40 (0.27–0.60)), long-acting (AHR = 0.60 (0.54–0.77)), and combination insulin treatment (AHR = 0.71 (0.58–0.86)) significantly reduced the risk of developing cancer at any site (all p<0.001)." (PMID 25978841, 2015). "In addition, studies utilizing pre-clinical models of multiple forms of cancer have found that response to insulin/IGF-targeting agents is associated with greater IGF-I and IGF-II levels." (PMID 26029167, 2015). "Recent reports on individuals carrying rare loss-of-function PTEN variants with a predisposition to a range of cancers (including endometrial) despite lower insulin levels may appear in conflict with our results." (PMID 26134033, 2015). "In 2009, the results of four large-scale epidemiological studies were published, raising the concern that insulin analogues, especially insulin glargine, might increase the risk of cancer." (PMID 26242987, 2015). "Finally, concerns have been recently raised about a possible link between long-acting insulin analogue (glargine) and increased risk of selected cancers." (PMID 26074956, 2015). "On the other hand, insulin, sulfonylureas and alpha glucosidase inhibitor use was associated with an increased risk of cancer incidence (RR = 1.21, 95% CI 1.08-1.36, I2 = 96.31%; RR = 1.20, 95% CI 1.13-1.27, I2 = 95.02%; RR = 1.10, 95% CI 1.05-1.15, I2 = 0.00% respectively)." (PMID 26076034, 2015). "Some studies suggested that patients using insulin glargine may have a higher risk of cancer than patients using human insulin." (PMID 26537234, 2015). "For example, metformin may reduce, while insulin and sulfonylureas may increase the risk of various types of cancer." (PMID 25303400, 2014). "At the same time, the transcriptome changes induced by CR in mice are enriched among genes showing age-related changes in primates, concentrated in specific expression patterns, and can be linked with specific functional pathways, including insulin signalling, cancer, and the immune response." (PMID 24400080, 2014). "Insulin use has been implicated as a risk factor for cancer." (PMID 24991802, 2014). "It still remains unclear whether initiating insulin in patients with a longer history of oral drug therapy alone does associates with increased cancer incidence and cancer mortality." (PMID 24667573, 2014).